CXCR4 (C-X-C motif chemokine receptor 4)
Diseases named in the same sentence as CXCR4 in open-access papers (continued):
Sharing a sentence is not in itself a finding about the gene and the disease.
focal segmental glomerulosclerosis (3 papers, 2014 to 2020). A renal disorder characterized by sclerotic lesions in the glomeruli. "We next investigated CXCR4 expression in humans with immunoglobulin A nephropathy (IgAN), rapidly progressive glomerulonephritis (RPGN) and focal segmental glomerulosclerosis (FSGS)." (PMID 32119183, 2020). "Expression of CXCR4 was observed to be increased in the kidneys of subtotally nephrectomized (SNx) rats and in biopsies from patients with secondary focal segmental glomerulosclerosis (FSGS), a rodent model and human correlate both characterized by aberration of the renal microvessels." (PMID 24637920, 2014). "To determine whether the SDF-1/CXCR4 pathway is similarly dysregulated in human CKD, we examined gene expression of both receptor and ligand in biopsies from patients with secondary focal segmental glomerulosclerosis (FSGS) and time zero live kidney donor controls." (PMID 24637920, 2014).
gout (3 papers, 2023 to 2025). A condition characterized by painful swelling of the joints, which is caused by deposition of urate crystals. "However, IL-18, one of the main proinflammatory cytokines related to the pathogenesis of gout, was significantly associated with the CXCR4 level." (PMID 36979628, 2023). "Nevertheless, the CXCL12/CXCR4 axis plays a critical role in immune-mediated or inflammatory diseases (including gouty arthritis) as a therapeutic target by modulating the inflammatory and immune response and regulating the recruitment of leukocytes." (PMID 36979628, 2023). "The CD4+ TCs and CD8+ TCs from gout remission were enriched in chemokines, such as CXCR4, as well as various antiinflammatory regulators (TNFAIP3, ZFP36, and SMAD7; an antagonist of TGF-β signaling)." (PMID 38063198, 2023). "In this study, we revealed that CXCL12 and CXCR4 were involved in the pathogenesis of uric acid-induced inflammation and gouty arthritis." (PMID 36979628, 2023). "In the present study, we confirmed that the IL-1β and IL-18 expression was increased by a stimulation with MSU crystals as well as in the blood of gout patients, together with CXCR4 and CXCL12." (PMID 36979628, 2023). "We evaluated the relationship among IL-1β, IL-18, CXCL12, CXCR4, and the laboratory variables in the patients with gout." (PMID 36979628, 2023). "Therefore, chemokine CXCL12 and its receptor CXCR4 might be considered to be potent therapeutic targets in uric acid-induced NLRP3 inflammasome activation in gout patients." (PMID 36979628, 2023). "The aim of this study was to evaluate the expression of chemokine receptor CXCR4 and its ligand CXCL12 in patients with gout and uric acid-induced inflammation." (PMID 36979628, 2023). "In a comparison of CXCR4 and its ligand CXCL12, the gout patients showed a larger increase in the expression of the serum CXCL12 level compared with the controls (392.27 ± 247.54 vs. 243.90 ± 184.03, p = 0.010)." (PMID 36979628, 2023). "First, the size of the study population, including the gout patients and controls, was relatively small to clarify the differences between CXCL12 and CXCR4." (PMID 36979628, 2023). "Considering the interactions between gout and the downstream pathways in the CXCL12/CXCR4 axis, many studies have suggested that the uric acid-induced inflammatory response with activation by NF-κB might be related to the GPCR downstream signaling pathway." (PMID 36979628, 2023). "Thus, the aim of this study was to compare the CXCR4 and CXCL12 levels between gout patients and controls and to determine the role of these molecules in uric acid-induced inflammation." (PMID 36979628, 2023).
hemangioblastoma (3 papers, 2016 to 2025). "The finding that CXCR4 expression was higher in sporadic hemangioblastomas is striking as in VHL-disease a germline mutation in VHL leads to a defect VHL protein which results in enhanced transcription of CXCR4, its ligand CXCL12 as well as VEGFA." (PMID 26920352, 2016). "We and others found CXCR4 overexpressed in hemangioblastoma cells compared to normal surrounding brain tissue." (PMID 26920352, 2016). "Most interestingly, sporadic hemangioblastomas overexpress CXCR4 compared to VHL-related hemangioblastoma." (PMID 26920352, 2016). "This is the first study in which expression of CXCR4, CXCL12, and VEGFA is compared in both sporadic and VHL associated hemangioblastoma patients." (PMID 26920352, 2016). "CXCR4 expression in hemangioblastoma tissue potentially creates treatment opportunities with drugs specifically targeting CXCR4 expressing cells." (PMID 26920352, 2016). "In sporadic hemangioblastomas the mean percentage of CXCR4 positive hemangioblastoma cells was 16 %, SD 8.4, in VHL-related hemangioblastomas 8 %, SD 4.4 (P = 0.002)." (PMID 26920352, 2016). "As the CXCR4 expression is limited to hemangioblastoma tissue, this potentially creates opportunities for treatment with drugs specifically targeting CXCR4 expressing cells." (PMID 26920352, 2016). "In the 16 sporadic hemangioblastomas the mean percentage of CXCR4 positive cells per specimen (16 %, range 1–38 %) was higher as compared to the 13 VHL-related hemangioblastomas (8 %, range 3–19 %, P = 0.002)." (PMID 26920352, 2016). "We aimed to determine in VHL-related and sporadic hemangioblastomas CXCR4, CXCL12, and VEGFA protein expression and to correlate this to hemangioblastoma size and expression in normal surrounding tissue." (PMID 26920352, 2016). "Sporadic hemangioblastomas express more CXCR4 as compared to VHL-related hemangioblastoma." (PMID 26920352, 2016). "Next we hypothesized that the size of hemangioblastomas at the time of surgery might explain the observed difference in CXCR4 expression and analyzed MRIs for hemangioblastoma size." (PMID 26920352, 2016). "Hemangioblastomas overexpress CXCR4, CXCL12, and VEGFA compared to normal surrounding tissue." (PMID 26920352, 2016). "For VHL-related hemangioblastoma, targeted therapy against CXCR4 and VEGFA could potentially be combined with conventional therapy as VHL-related disease is multiple and lesions often reoccur after surgery." (PMID 26920352, 2016). "Earlier studies in VHL related hemangioblastoma found upregulated CXCR4, CXCL12, and VEGFA." (PMID 26920352, 2016). "Hemangioblastomas are usually positive for alpha-inhibin, D2-40, brachyury, NSE, NCAM1, S100, ezrin, CXCR4, aquaporin-1, and occasionally for GFAP and EGFR, and negative for EMA, CD10 and CAM5.2." (PMID 41302074, 2025). "Subsequently, HIF-VEGF-VEGFR2, HIF-EPO, HIF-CAIX, HIF-SDF1β-CXCR4, HIF-EphB4/EphrinB2, and HIF-Notch/Dll4 are thought to play critical roles in angiogenesis in hemangioblastoma." (PMID 39850947, 2024). "This study shows that CXCR4, CXCL12, and VEGFA are all overexpressed in stromal hemangioblastoma cells compared to normal surrounding brain tissue." (PMID 26920352, 2016). "CXCR4, CXCL12, and VEGFA were all overexpressed in hemangioblastomas as compared to normal surrounding tissue." (PMID 26920352, 2016). "Compared to normal surrounding tissue CXCR4, CXCL12, and VEGFA were overexpressed in hemangioblastomas." (PMID 26920352, 2016). "All hemangioblastoma cells, excluding endothelial cells, showed CXCR4 expression (n = 29, as 4 slides were not evaluable)." (PMID 26920352, 2016). "Therefore, the aim of this study was to investigate CXCR4, CXCL12, and VEGFA protein expression in VHL-related and sporadic hemangioblastomas and to correlate this to size as measured by MRI before surgery to investigate possible differences between VHL-related and sporadic hemangioblastoma." (PMID 26920352, 2016).
hemorrhage (3 papers, 2017 to 2020). Loss of blood from the vascular compartment to the exterior or into nonvascular body space as a result of rupture or severance of the blood vessels. "In the present study, we evaluated the pharmacodynamic properties of various CXCR4 protein agonists in a rat model of lung ischemia–reperfusion injury and hemorrhage induced ARDS." (PMID 32647374, 2020).
idiopathic inflammatory myopathy (3 papers, 2009 to 2021). Idiopathic form of inflammatory myopathy. "The chemokine receptor 4 (CXCR4) has been observed more specifically in some idiopathic inflammatory myopathies in humans." (PMID 19664222, 2009).
invasive carcinoma (3 papers, 2013 to 2024). A carcinoma that is not confined to the epithelium, and has spread to the surrounding stroma. "Pooled expression prevalence rates of carcinoma in situ were at least comparable to (GLUT1 and IGF1R) or higher than (CAIX and CXCR4) invasive carcinoma, albeit based on few studies." (PMID 24206539, 2013). "The concurrent expression of SDF-1 and CXCR4 at sites of early or advanced invasive carcinoma and liver metastases highlighted the clinical significance in terms of SDF-1/CXCR4 signaling, acting as a robust predictor of liver metastasis and profoundly affecting the overall prognosis of CRC patients." (PMID 39195225, 2024). "In all cases from benign disease to invasive carcinoma, the concentrations of CXCL8, CXCR4 and CXCL12 were significantly different." (PMID 37208442, 2023).
kidney cancer (3 papers, 2002 to 2020). Primary or metastatic malignant neoplasm involving the kidney. "In the present study, we found an upregulated expression of CXCR4 mRNA in kidney cancer samples compared to adjacent normal tissue." (PMID 11953881, 2002). "Therefore, we analysed CXCL12α/CXCR4 expression and function in four human kidney cancer cell lines (A-498, CAKI-1, CAKI-2, HA-7), 10 freshly harvested human tumour samples and corresponding normal kidney tissue." (PMID 11953881, 2002). "Thus, we have investigated the expression of CXC-chemokine receptors on primary RCC cultures and on kidney cancer compared to normal kidney tissue, detecting an alteration of the CXCL12/CXCR4 signalling pathway in kidney cancer." (PMID 11953881, 2002). "As the pattern of metastasis between breast and kidney cancer are comparable at least to some extent, similar mechanism of CXCR4/CXCL12 in tumour spread might also be active." (PMID 11953881, 2002). "In the present study, which is the first to evaluate CXCL12/CXCR4 expression and its potential function in RCC, CXCL12α expression was decreased in kidney cancer compared to normal kidney tissue." (PMID 11953881, 2002).
Lewis lung carcinoma (3 papers, 2013 to 2023). "CXCR4+ cells from the Lewis lung carcinoma cell line exhibit cancer metastatic stem cell characteristics." (PMID 28903328, 2017). "In our previous study, CXCR4-positive cells from the Lewis lung carcinoma (LLC) cell line presented with cancer metastatic stem cell characteristics, and miR-223 expression was reduced compared with in CXCR4-negative cells." (PMID 24137330, 2013).
Lymphadenopathy (3 papers, 2016 to 2023). Enlargement (swelling) of a lymph node. "Patients with CXCR4 mutations had lower rates of lymphadenopathy than patients without CXCR4 mutations (14% and 50%; p = 0.04)." (PMID 34531537, 2022). "Since enlarged lymph nodes, as CLL major proliferation sites, are an important clinical indicator of progression, we next investigated BCR-mediated CXCR4 downregulation capacity in patients presenting or not with lymphadenopathy." (PMID 27127886, 2016).
lymphoproliferative disorders (3 papers, 2016 to 2025). "CXCR4-targeted imaging agents have also been developed and a 68Ga-labeled CXCR4 binding peptide has shown promising results in lymphoproliferative disorders in patients." (PMID 26848769, 2016).
malignant mesothelioma (3 papers, 2011 to 2024). A malignant neoplasm of the pleura or peritoneum, arising from mesothelial cells. "The use of BoxA, or a small molecule mimicking its action on CXCR4, may hold promise for malignant mesothelioma, for which there are very few available therapeutic interventions, and more generally for the wide variety of tumors vulnerable to CD47 blockade." (PMID 33956406, 2021).
mammary adenocarcinoma (3 papers, 2011 to 2017). "Using the rat mammary adenocarcinoma cell line MTLn3, we studied the effects of overexpression of CXCR4 and CXCR7 on CXCL12-induced chemotaxis and invasion, as well as in vivo motility, intravasation and metastasis formation." (PMID 22152016, 2011). "We overexpressed CXCR4, CXCR7 or both in the rat mammary adenocarcinoma cell line MTLn3." (PMID 22152016, 2011).
medullary thyroid cancer (3 papers, 2021 to 2022). "In radiation-induced medullary carcinoma in 4W rats, the expression of Cdkn2a and Cxcr4 increased, whereas that of seven autophagy regulatory genes (Dapk1, Eif2ak3, Gaa, Hgs, Mapkl4, Mapt, and Pim2) and five autophagy machinery components (Atg4b, Atg5, Gabarapl2, Rab24, and Wipi1) decreased." (PMID 34580369, 2021). "Some complementary binding sites between miR-455-5p and CXCL12 have been found, and a significant inverse correlation has been detected as well, indicating that miR-455-5p might suppress medullary thyroid cancer growth and metastasis by targeting CXCL12/CXCR4 signaling pathway." (PMID 35647303, 2022).
monoclonal gammopathies (3 papers, 2018 to 2020). "In this study, we evaluated the role of peripheral blood (PB) cell-free DNA (cfDNA) in characterizing the mutational status of MYD88 and CXCR4 of patients with IgM monoclonal gammopathies." (PMID 30026568, 2018). "In conclusion, the use of PB cfDNA provides a minimally invasive, but informative and sensitive tool for the assessment of mutational status of MYD88 and CXCR4 of patients with IgM monoclonal gammopathies." (PMID 30026568, 2018). "This is the first study to evaluate the feasibility of detecting somatic mutations of MYD88 and CXCR4 in the cfDNA derived from the PB plasma of patients with IgM monoclonal gammopathies." (PMID 30026568, 2018). "The aim of our study was to investigate the role of cfDNA in the characterization of the mutational status of MYD88 and CXCR4 of patients with IgM monoclonal gammopathies." (PMID 30026568, 2018). "Of the 98 patients with IgM monoclonal gammopathies, mutational screening of CXCR4 gene could be evaluated in 79 patients with cfDNA (79/98 patients, 80%) and in 73 patients with tDNA (73/98 patients, 74%)." (PMID 30026568, 2018). "In our study, we found that in patients with IgM monoclonal gammopathies the MYD88L265P mutation and mutations in CXCR4 gene in cfDNA can be detected with a high concordance of 94 and 90%, respectively, compared to those detected in the tDNA." (PMID 30026568, 2018). "Both MYD88 and CXCR4 mutations are detected in the bone marrow (BM), although there have been attempts to detect them in CD19+-selected cells in the peripheral blood (PB) of patients with IgM monoclonal gammopathies." (PMID 30026568, 2018).
myeloproliferative neoplasm (3 papers, 2015 to 2021). A clonal hematopoietic stem cell disorder, characterized by proliferation in the bone marrow of one or more of the myeloid (i.e., granulocytic, erythroid, megakaryocytic, and mast cell) lineages. "This is the first data that shows the feasibility of CXCR4-directed imaging with 68Ga-Pentixafor PET/CT in a myeloproliferative neoplasm patient cohort." (PMID 34445532, 2021). "In particular, miR-146a, whose deletion in mouse models leads to myeloproliferative disorders 38–40, may target uPAR/CXCR4 also in human AML and, thus, might represent a useful tool in therapeutical approaches." (PMID 26082201, 2015).
nephritis (3 papers, 2018 to 2021). Inflammation of renal tissue. "The authors demonstrated that in mice with active nephritis, CXCR4 was significantly upregulated on monocytes, neutrophils, B cell subsets, and plasma cells." (PMID 34744730, 2021).
neuropathic pain (3 papers, 2018 to 2022). Chronic pain caused by damage to nerve fibers. "Previous studies have demonstrated that the CXCL12/CXCR4 signaling axis is involved in the regulation of neuropathic pain (NP)." (PMID 30955244, 2019). "We found that CXCR4 was markedly decreased in naïve mice or the increased CXCR4 was reversed in pSNL-induced neuropathic pain mice 2 days after intrathecal injection of CXCR4-siRNA (data not shown)." (PMID 29386025, 2018). "Based on the fact that miR-23a/CXCR4 regulates neuropathic pain by directly targeting TXNIP and TXNIP regulates the expression of NLRP3 inflammasome in neuropathic pain, we supposed to investigate whether miR-23a or CXCR4 could regulate NLRP3 inflammasome via TXNIP." (PMID 29386025, 2018). "Therefore, the present study aimed to determine the functional and regulatory role of miR-23a in pain processing in the CNS and its interplay with CXCR4 and TXNIP at spinal level, which may provide potential therapeutic targets for peripheral injury-induced neuropathic pain." (PMID 29386025, 2018).
osteogenesis imperfecta (3 papers, 2014 to 2017). Osteogenesis imperfecta (OI) comprises a heterogeneous group of genetic disorders characterized by increased bone fragility, low bone mass, and susceptibility to bone fractures with variable severity. "Furthermore, enabling MSCs to be better migrators toward injured tissue is another application of preconditioning by Jones and colleagues via upregulation of CXCR4 expression in a model of osteogenesis imperfecta." (PMID 25376815, 2014).
ovarian epithelial tumor (3 papers, 2014 to 2024). A benign, borderline, or malignant tumor that originates from the surface epithelium of the ovary. "Another study showed that the positive rate of CXCR4 in malignant epithelial tumors was significantly higher than that in normal ovarian epithelial tumors, benign epithelial tumors and borderline epithelial tumors (CXCR4:80% vs. 0, 15%, 40%)." (PMID 39281319, 2024). "However, it should be mentioned that earlier studies have implicated tissue hypoxia (which may be present in epithelial ovarian tumors) as a potent factor in upregulating the expression of SDF-1 and CXCR4 in various cells and organs." (PMID 24765189, 2014).
Pain (3 papers, 2014 to 2022). An unpleasant sensory and emotional experience associated with actual or potential tissue damage, or described in terms of such damage. "Intraperitoneal injection of AMD3100 reversed thermal hyperalgesia and mechanical allodynia and downregulated CXCR4 in the spinal cord dorsal horn of rats undergoing DNP at the early phase as was reported in other neuropathic pain models." (PMID 35799894, 2022). "Therefore, in this study, we aimed to explore the roles and mechanisms of central CXCR4 in pain modulation using specific CXCR4 antagonist AMD3100 and a peripheral neuropathic pain (PNP) model using partial sciatic nerve ligation (pSNL) in mice." (PMID 25119456, 2014).
pancreatitis (3 papers, 2015 to 2024). Inflammation of the pancreas. "A previous study indicated that CXCL12/CXCR4 axis activation contributed to the progression of fibrosis during experimental pancreatitis." (PMID 38769308, 2024). "To examine this, we treated the Reg4−/− mice with the CXCR4 antagonist plerixafor (AMD3100) with two daily injections (2.5 mg/kg body weight) initiated 1 day before the induction of pancreatitis and which lasted until day 7 when the mice were sacrificed." (PMID 38769308, 2024). "Reg4 ablation may increase CXCL12/CXCR4 axis activation during pancreatitis and thereby potentially lead to stimulated TGF-β/SMADs profibrotic signaling, and this might then activate pancreatic stellate cells." (PMID 38769308, 2024). "Therefore, we confirmed that the SDF-1α/CXCR4 axis is involved in the upregulation of VEGF expression in pancreatitis tissues." (PMID 25810724, 2015). "Indeed, CXCR4 inhibition attenuated the phosphorylation of Smad2/3 during pancreatitis." (PMID 38769308, 2024). "In this pancreatitis-related pain model, adult monocyte-derived macrophages migrate into the pancreatic tissue during the early stage of tissue damage or inflammation, and secrete HMGB1, which in turn activates RAGE and accelerates CXCL12/CXCR4 signaling, resulting in pancreatic pain." (PMID 34440650, 2021).